TIMP3 (TIMP metallopeptidase inhibitor 3)
Description:
Mediates a variety of processes including matrix regulation and turnover, inflammation, and angiogenesis, through reversible inhibition of zinc protease superfamily enzymes, primarily matrix metalloproteinases (MMPs). Regulates extracellular matrix (ECM) remodeling through inhibition of matrix metalloproteinases (MMP) including MMP-1, MMP-2, MMP-3, MMP-7, MMP-9, MMP-13, MMP-14 and MMP-15. Additionally, modulates the processing of amyloid precursor protein (APP) and apolipoprotein E receptor ApoER2 by inhibiting two alpha-secretases ADAM10 and ADAM17. Functions as a tumor suppressor and a potent inhibitor of angiogenesis. Exerts its anti-angiogenic effect by directly interacting with vascular endothelial growth factor (VEGF) receptor-2/KDR, preventing its binding to the VEGFA ligand. Selectively induces apoptosis in angiogenic endothelial cells through a caspase-independent cell death pathway. Mechanistically, inhibits matrix-induced focal adhesion kinase PTK2 tyrosine phosphorylation and association with paxillin/PXN and disrupts the incorporation of ITGB3, PTK2 and PXN into focal adhesion contacts on the matrix.
Synonyms: HSMRK222; K222; K222TA2; SFD
Tractability: Antibody: its Gene Ontology location is reachable by antibodies, with high confidence; UniProt places it where antibodies can reach, with medium confidence; UniProt predicts a signal peptide or a membrane-spanning region. PROTAC: a small molecule that binds it is known.
Gene: Protein-coding gene on chromosome 22 (32,801,576 to 32,863,042, forward strand). Ensembl gene ENSG00000100234.
Subcellular location: Secreted, extracellular space, extracellular matrix
Subcellular location (Human Protein Atlas): Vesicles; Golgi apparatus; Predicted to be secreted
Pathways (Reactome):
Hemostasis: Platelet degranulation
Gene Ontology:
Molecular function: protein binding; metalloendopeptidase inhibitor activity
Biological process: negative regulation of membrane protein ectodomain proteolysis; negative regulation of extracellular matrix disassembly; response to cytokine; response to hormone; negative regulation of proteolysis
Cellular component: extracellular matrix; nucleus; extracellular region; platelet dense granule lumen; basement membrane; secretory granule lumen
Genetic constraint (gnomAD): Loss-of-function variants: 10 observed, 25.69 expected, observed/expected ratio (o/e) 0.39, 90% interval 0.24 to 0.66. The upper end of that interval is the gene's LOEUF score, 0.66, which puts it in group 2 of 6, group 1 being the genes least tolerant of losing a copy. Missense variants: 177 observed, 263.62 expected, observed/expected ratio (o/e) 0.67, 90% interval 0.59 to 0.76. Synonymous variants: 110 observed, 105.4 expected, observed/expected ratio (o/e) 1.04, 90% interval 0.89 to 1.22.
Gene-disease validity (ClinGen):
ClinGen rates the evidence that TIMP3 causes each of these diseases.
Sorsby fundus dystrophy (autosomal dominant): Definitive. Sorsby's fundus dystrophy is a rare progressive autosomal dominant macular dystrophy, presenting between the third and sixth decades of life, characterized by retinal atrophy and retinal detachment and leading to loss of central vision, then peripheral vision, and eventually blindness.
Homologues: Orthologues: chimpanzee TIMP3 (100% identical), macaque TIMP3 (100% identical), pig TIMP3 (99% identical), guinea pig TIMP3 (98% identical), dog TIMP3 (97% identical), mouse Timp3 (96% identical), rabbit TIMP3 (95% identical), rat Timp3 (95% identical), tropical clawed frog timp1 (37% identical), Drosophila melanogaster Timp (24% identical), Caenorhabditis elegans cri-2 (20% identical). Paralogues in human: TIMP4 (46% identical), TIMP2 (45% identical), TIMP1 (36% identical).
Diseases named in the same sentence as TIMP3 in open-access papers:
TIMP3 is named in the same sentence as 319 diseases in open-access papers, as found by Europe PMC text mining. Sharing a sentence is not in itself a finding about the gene and the disease. The quoted sentences say what the papers report.
breast cancer (85 papers, 2006 to 2025). A primary or metastatic malignant neoplasm involving the breast. "TIMP3 has been associated with cervical adenocarcinoma as well as cancer development in serous ovarian cancer and breast cancer metastasis." (PMID 38542164, 2024). "We then consolidated an OPN pathway and upregulated gene signatures from our findings (Spp1, Timp3, Col11a1, Mmp9, Mmp2, Fn1, Cd44, and Il-4) to interrogate how their predicted activity is associated with relapse-free survival in breast cancer patients." (PMID 39448577, 2024). "Because TIMP-3 genetic variants have been reported to be correlated with breast cancer prognosis 41, 42, we further investigated the association of TIMP-3 SNPs with patient survival in cervical cancer." (PMID 35813301, 2022). "In contrast, Timp3 loss suppressed tumorigenesis in mouse models of human breast cancer, suggesting the tumor-promoting role of TIMP-3 in vivo." (PMID 36741729, 2022). "Previous literature studies have shown that the C allele of TIMP3 rs9619311 is associated with poor five-year survival in uterine cervical cancer patients, increased risk of breast cancer, and protection against hepatocellular carcinoma in women." (PMID 36612628, 2022). "Consistent lowly expressed TIMP3 was previously reported in NPC tissues, while knockdown of TIMP3 methylation was associated with alleviation of breast cancer." (PMID 36061358, 2022). "As for TIMP-3, stromal TIMP-3 expression is a poor prognostic factor in breast cancer, while high TIMP-3 mRNA levels are associated with favorable prognosis." (PMID 36741729, 2022). "Tumour suppressor genes RASSF1A (Ras‐association domain family 1, isoform A) and TIMP3 are frequently down‐regulated in breast cancer." (PMID 28524540, 2017). "We have taken a genetic approach to determine the impact of Timp3 loss on two mouse models of breast cancer." (PMID 25807548, 2015). "Altogether these data have led to the surprising finding that a stepwise loss of one or both alleles of Timp3 delays or halts mammary cancer in two independent models of luminal breast cancer." (PMID 25807548, 2015). "We observed profound mammary tumor suppression in the Timp3 deficient cohort (Neu Timp3−⁄−) and decreased tumor incidence." (PMID 25807548, 2015). "Our work utilizes a genetic approach to determine the impact of Timp3 loss in epithelial and stromal compartments as well as during mammary tumor initiation and progression." (PMID 25807548, 2015). "In parallel, we investigated the impact of Timp3 loss on Her2-driven breast cancer, an oncogene overexpressed in ~25% of human breast cancer." (PMID 25807548, 2015). "The present study demonstrated that, in a univariate analysis, TIMP-3 expression was significantly associated with shortened disease-free survival in patients with breast carcinoma." (PMID 25510449, 2014). "SNPs in TIMP3 have been associated with breast cancer prognosis however, this study is the first report of an association between TIMP3 polymorphisms and survival of gastric or esophageal cancer patients." (PMID 23527119, 2013). "It has also been published that high TIMP-3 mRNA levels are associated with a good prognosis in breast cancer." (PMID 17342087, 2007). "In breast cancer mice model, deficient of Timp3 could resist developing of breast cancer by inhibiting tumor cell's growth." (PMID 34093812, 2021). "Thus, in future studies, a larger cohort and in vivo experiments should be conducted to further elucidate the underlying mechanism associated with lncRNA ROR, MLL1, H3K4 methylation and TIMP3 in breast cancer." (PMID 33653378, 2021). "Detailed investigation of C02S revealed that it could induce reexpression of p16, p21 and TIMP3 and cause DNA damages, modulate multiple cancer hallmarks simultaneously and exert tumor growth suppression in mouse breast cancer models." (PMID 33840388, 2021). "To investigate whether the TIMP3 deficient mammary tumor phenotype involves TNF we undertook a genetic approach." (PMID 25807548, 2015).
breast cancer (continued). "Two independent models show that the loss of Timp3 results in mammary tumor suppression." (PMID 25807548, 2015). "Thus, the loss of Timp3 from the host stroma specifically inhibits the early steps of tumor progression in spontaneous breast cancer models of Timp3 null mice." (PMID 25807548, 2015). "Other studies reported that TIMP1 levels correlate positively with higher serum HER-2 levels, increased metastasis and reduced survival in breast cancer patients, whereas TIMP3 over-expression was associated with successful adjuvant endocrine therapy, good prognosis and longer disease-free survival." (PMID 22276018, 2009). "Some evidence also suggests a role for TIMP3 as a breast cancer risk marker as TIMP3 levels were higher in mammographically dense breasts, which are considered to be at higher risk for developing breast cancer." (PMID 22276018, 2009). "Both MMP-13 and TIMP-3 have been implicated in breast cancer." (PMID 19405959, 2009). "The HMG-box transcription factor 1/TIMP metallopeptidase inhibitor 3/PTEN axis inhibits the tumorigenesis of breast cancer and promotes the sensitivity of breast cancer to radiotherapy and hormone therapy." (PMID 39991583, 2025). "Breast cancer patients with relatively high levels of TIMP3 mRNA have longer disease-free survival (DFS) and better responses to tamoxifen." (PMID 38542164, 2024). "miR-29c upregulated TIMP3 expression in breast cancer cells by downregulating DNA methyltransferase 3B (DMNT3B, a DNA methyltransferase)." (PMID 38542164, 2024). "The proteins encoded by the PDCD-4, FasL, PTEN and RhoB genes are related to the regulation of breast cancer cell proliferation, and the proteins encoded by the Maspin, TIMP3 and RECK genes are related to the regulation of breast cancer cell invasion." (PMID 38041032, 2023). "Knockdown of lncRNA ROR regulates the division, death and invasion of breast cancer cells by inhibiting TIMP3." (PMID 36843929, 2023). "The TIMP-3 suppression in breast cancer cells is mediated by epigenetic silencing mechanisms, including the increased activity of the enhancer of zeste homolog 2 (EZH2) and class I HDACs, which is independent of promoter DNA hypermethylation." (PMID 35327559, 2022). "Tissue inhibitor of metalloproteinase-3 (TIMP3) has been reported to suppress the metastasis of glioma cells and breast cancer cells." (PMID 35295323, 2022). "In comparison to the adjacent tissues, the expression of TIMP3 in breast cancer tissues was increased." (PMID 33653378, 2021). "Following the overexpression and silencing of lncRNA ROR in breast cancer, ChIP was performed to detect the enrichment of H3K4me3 on the TIMP3 promoter." (PMID 33653378, 2021). "Next, compared with the cells transfected with sh-NC, the proliferation and invasion ability of breast cancer cells transfected with sh-TIMP3 were dramatically decreased, while apoptosis was notably increased." (PMID 33653378, 2021). "The results obtained indicated that the expression of lncRNA ROR and TIMP3 was higher in breast cancer tissues than that in the adjacent tissues (p < 0.05)." (PMID 33653378, 2021). "The results suggested that lncRNA ROR knockdown regulated proliferation, apoptosis and invasion of breast cancer cells by inhibiting TIMP3." (PMID 33653378, 2021). "TIMP3 promoter methylation has been newly identified as an epigenetic candidate for BRCA1ness breast cancer therapy." (PMID 33653378, 2021). "The findings of our study provide evidence illustrating that lncRNA ROR decoys transmethylase MLL1 to promote H3K4 methylation and up-regulate TIMP3, consequently promoting the progression of breast cancer." (PMID 33653378, 2021). "Taken together, the key findings of our study provide evidence illustrating the role of lncRNA ROR as an oncogene in breast cancer via the recruitment of transmethylase MLL1 to the TIMP3 promoter region, elevating TIMP3 level." (PMID 33653378, 2021).
breast cancer (continued). "For example, breast cancer cell lines grown on Matrigel showed that methylation of the TIMP3 promoter and changes in expression of TIMP3 and DNMT3B were all affected by miR-29c regulation." (PMID 34576261, 2021). "Decreased levels of TIMP‐3 have been shown in various human malignancies including breast cancer, prostate cancer, gastric cancer, esophageal squamous cell carcinoma, endometrial cancer, and cholangiocarcinomas." (PMID 32744429, 2020). "This is firstly reported that miR-29c inhibited the proliferation, migration, invasion colony, and 3D growth of breast cancer cells by targeting TIMP3/STAT1/FOXO1 pathway." (PMID 29796115, 2018). "We firstly illustrated that miR-29c exerted its regulatory function in breast cancers by activating the TIMP3/STAT1/FOXO1 pathway." (PMID 29796115, 2018). "Once spatiotemporal distributions of MMPs, ADAMs, and TIMP3 were identified during mammary tumor progression are revealed, the TIMP3 effects on each target protease can be understood." (PMID 29651417, 2018). "It was proven that TIMP3 overexpression led to apoptosis in vitro and increased apoptosis in human breast cancer cells (MDA-MB435)." (PMID 29304854, 2018). "Acylglycerol kinase was reported to promote the growth of cells and tumorigenicity in breast cancer by inhibiting the expression of FOXO1.TIMP3 is a versatile extracellular regulator in cancers." (PMID 29796115, 2018). "All together, these results suggest that miR-29c inhibits breast cancer by targeting the DNMT3B/TIMP3/STAT1/FOXO1 pathway." (PMID 29796115, 2018). "We firstly reported that miR-29c plays a significant role in suppressing the progression of breast cancers by targeting the TIMP3/STAT1/FOXO1 pathway." (PMID 29796115, 2018). "Text mining of PubMed literature with an R package RISmed revealed that most of them are with unclear roles in breast cancer except for Igfbp3, Mmp14, Fap, Timp3 and Wnt5a." (PMID 29615825, 2018). "Taken together, we show that paracrinal inhibin βA secretion by breast cancer cells, which is regulated by miR-218, alters the processing of procollagen during osteoblast differentiation through regulating Timp3 expression." (PMID 30348200, 2018). "The down-regulation of miR-221/222 significantly increases the expression of TIMP3 and enhances the sensitivity of breast cancer cells to tamoxifen." (PMID 28477009, 2017). "For example, TIMP-3 appears able to induce apoptosis in melanoma cells, retinal pigment epithelial cells, and breast cancer cells." (PMID 29137364, 2017). "TET1, a dioxygenase involved in cytosine demethylation, activates TIMP3 expression in breast cancer cells." (PMID 27058897, 2016). "Significantly, low levels of tissue inhibitor of matrix metalloproteinase-3 (TIMP-3) protein expression in breast cancer has been reported to be correlated with an aggressive cancer phenotype." (PMID 27999314, 2016). "Here we conclude that Timp3, Tnf and Tnfr1 similarly promote breast cancer onset with varying effects on tumor progression." (PMID 25807548, 2015). "This applies across all breast cancer subtypes, and decreased Timp3 expression is observed in the more aggressive, hormone receptor negative subset and is correlated with therapeutic success." (PMID 25807548, 2015). "To further investigate the effects of diets, we have analyzed the expression of the tumor suppressor genes RASSF1A and TIMP3, which have important roles on the key hallmarks that a neoplastic cell acquires, and are frequently down-regulated in breast cancer." (PMID 26401660, 2015). "Our study underscores the importance of Timp3 in the mammary gland revealing unexpected but important influences on breast cancer development." (PMID 25807548, 2015). "Timp3 is commonly silenced in breast cancer, but mechanistic studies have identified both tumor promotion and suppression effects of this gene." (PMID 25807548, 2015).
breast cancer (continued). "Given the requirement for Tnfr1 in Timp3 regulation of breast cancer it is possible that the increased shedding of Tnfr1 from mammary epithelial cells participates during suppression." (PMID 25807548, 2015). "TIMP3 promoter methylation has been described in a wide range of tumors, including kidney, esophagus, colon, and breast cancer 40–43." (PMID 25065733, 2014). "A recent study showed for the first time that miR-21 negatively regulates TIMP3 expression in breast cancer via the binding of the 3′UTR of TIMP3 mRNA and promotes breast cancer invasion in multiple cell lines in vitro." (PMID 22200848, 2012). "Using hierarchical clustering in the plasma samples cohort, we found significant promoter hypermethylation of eight genes (APC, BIN1, BRCA1, CST6, GSTP1, P16, P21 and TIMP3) in patients' plasma of breast cancer patients compared with plasma of normal subjects." (PMID 21283676, 2011). "Evaluation of the activities of TIMP-1, TIMP-2 and TIMP-3 in canine mammary tumor samples by reverse zymography has shown that low activity can be correlated with a malignant phenotype." (PMID 21726449, 2011). "Several cancer-related genes have been reported to be silenced by aberrant methylation in breast cancer, such as 14-3-3 s, E-cadherin and tissue inhibitor of metalloproteinase 3 (TIMP3) genes." (PMID 20132554, 2010). "Treatment with 5-aza-dc activated the expression of 14-3-3 s and E-cadherin genes in breast carcinoma cells and of TIMP3 in different tumor cell lines." (PMID 20132554, 2010). "Some reports show that TIMP3 plays a vital role in breast cancer." (PMID 38542164, 2024). "Finally, the proliferation, migration, invasion, colony formation and growth of breast cancer are mediated by TIMP3/STAT1/FOXO1." (PMID 37298314, 2023). "TIMP-3 overexpression inhibited cell growth and induced apoptosis in breast cancer cells in vitro." (PMID 36741729, 2022). "MiRNAs are also involved in the downregulation of TIMP-1 and TIMP-3 in breast cancer." (PMID 34445715, 2021). "In order to verify this hypothesis, the expression of TIMP3 in breast cancer tissues and adjacent normal tissues was initially determined by RT-qPCR." (PMID 33653378, 2021). "The rescue experiments demonstrated that lncRNA ROR knockdown could inhibit the progression of breast cancer via the downregulation of TIMP3." (PMID 33653378, 2021). "TIMP3 showed a varied level of expression in the breast cancer cells of the GOBO database." (PMID 29744893, 2018). "In addition, the direct binding of miR-29c to the wild-type 3′UTR of DNTM3B indicates that miR-29c is the direct post-transcriptional regulator of DNMT3B, which is elevated in breast cancer and methylates the promoter of the TIMP3 gene." (PMID 29796115, 2018). "However, it is unclear that TIMP3 inhibits the progress of breast cancer via the FOXO1/STAT1 pathway." (PMID 29796115, 2018). "Upregulated DNMT3B is critical for promoter methylation and decreased expression of TIMP3, which could promote progression of breast cancer via the TIMP3/STAT1/FOXO1 pathway." (PMID 29796115, 2018). "Finally, our results showed that miR-29c exerted its function in breast cancers by regulating the TIMP3/STAT1/FOXO1 pathway." (PMID 29796115, 2018). "These biological characteristics are strikingly similar to the mammary glands of Mmtv-Ccl2 transgenic mice, in which overexpression of CCL2 caused increased abundance of stroma, collagen thickness, mRNA encoding TIMP3 and elevated risk of DMBA-induced mammary cancer." (PMID 28077158, 2017). "Here we have described the unexpected impact of Timp3 in mouse models of human breast cancer." (PMID 25807548, 2015). "The regulation of TNF signaling by TIMP3 may comprise an important step in tumor development as revealed in both PyMT and Neu models of breast cancer." (PMID 25807548, 2015). "These contradictory studies have left the role of TIMP3 in breast cancer undefined." (PMID 25807548, 2015).